IGF1 (insulin like growth factor 1)
Diseases named in the same sentence as IGF1 in open-access papers (continued):
Sharing a sentence is not in itself a finding about the gene and the disease.
Insulin resistance (continued). "Chronic exercise reduces insulin resistance even in individuals with impaired glucose tolerance, decreases IGF-1 levels, and increases its binding proteins." (PMID 37958310, 2023). "GH/IGF-1 affects carbohydrate and lipid metabolism and have opposite effects: IGF-1 stimulates glucose uptake and facilitates insulin signaling, while GH induces lipolysis, which induces insulin resistance and elevated levels of free fatty acids (FFAs)." (PMID 37424859, 2023). "Type 2 diabetics exhibit a phenomenon of an increase in levels of IGF-1 (insulin-like growth factor-1) due to insulin resistance, which can result in carcinogenesis and oxidative stress due to persistent hyperglycemia." (PMID 38149129, 2023). "Treatment with a growth hormone-releasing hormone antagonist in liver-specific deletion of Igf-1 mice reverses the increased p85α production in skeletal muscle and insulin resistance phenotype." (PMID 37628845, 2023). "Up-regulation of insulin secretion and insulin resistance results in elevated IGF-1 production and bioavailability, resulting in cell proliferation and tumor growth." (PMID 36617570, 2023). "Increased production of androgens in theca cells promotes the secretion of insulin-like growth factor 1 (IGF1) and insulin resistance reduces the secretion of the globulin that binds sex hormones (SHBG) in the liver." (PMID 37189616, 2023). "Third, decreased levels of adiponectin lead to marked insulin resistance and subsequent increased levels of IGF-1." (PMID 37467012, 2023). "The hormonal framework for this metabolic environment is the high concentration of growth hormone (GH), the low concentration of insulin in connection with GH-dependent insulin resistance and the low concentration of IGF-1, the so-called GH-IGF-1 axis." (PMID 37835703, 2023). "While insulin resistance increases with aging and thus is generally unfavorable, klotho’s role in inhibiting the insulin/IGF-1 pathway is to decrease lipid overload since lipid-laden cells are vulnerable to lipid-induced programmed cell death." (PMID 37746149, 2023). "In this study, we explored the relationship between insulin resistance, metabolic indices that characterize MetS, and IGF-1 levels in BC survivors." (PMID 37106164, 2023). "BC is correlated with insulin resistance and high insulin levels; one proposed mechanism by which CR inhibits tumor growth is its modulation of circulating levels of free IGF-1 in the serum, responsible for malignant transformation and neo-angiogenesis." (PMID 37960330, 2023). "It is reported to be involved in various biological pathways such as increased insulin resistance, uncoupling of the GH/IGF1 axis, and an increase in mammary cell proliferation to improve metabolic health and milk yield." (PMID 36899741, 2023). "Metabolic factors such as a high-fat diet, obesity, and diabetes mellitus are closely related to insulin resistance and hyperinsulinemia, which increase the expression of insulin and insulin-like growth factor-1." (PMID 37637156, 2023). "Induction of insulin signaling with IGF-1 and reversal of insulin resistance suppresses α-synuclein aggregation and toxicity." (PMID 37746149, 2023). "NS attenuates insulin resistance, enhances insulin signaling, suppresses cyclooxygenase-2, upregulates insulin-like growth factor-1, and prevents endothelial dysfunction in DM." (PMID 37818339, 2023). "IGF-1 level decreases when insulin resistance occurs, leading to lipid deposition in intramuscular and intermuscular adipose cells, increased infiltration of adipose between muscle bundles, and aggravated damage to muscle cells." (PMID 37424859, 2023). "It exerts an indirect effect via decreasing insulin resistance and insulin-like growth factor 1 (IGF-1) levels." (PMID 37275952, 2023).
Insulin resistance (continued). "Improving insulin resistance, PA interferes with the serum levels of several tumor-promoting proteins such as insulin-like growth factor-1 and, while reducing adiposity, it decreases blood levels of proinflammatory adipokines." (PMID 36677036, 2023). "Third, the insulin growth factor-1 (IGF-1) axis is activated by insulin resistance (IR) and create a microenvironment conducive to cancer development." (PMID 37185400, 2023). "Insulin resistance, hyperinsulinemia, hyperglycemia, and elevated levels of IGF-1 activate PaSCs that express IGF-R." (PMID 37373743, 2023). "While L. digitata reduced glucose, increasing in parallel IGF-1, both insulin and insulin resistance index were unaffected by diets, suggesting the maintenance of glycaemia homeostasis." (PMID 37087466, 2023). "Mechanistically, insulin resistance (IR) results in hyperinsulinemia as well as the activation of the insulin receptor and insulin-like growth factor 1 (IGF-1) signaling pathways, which are important initiators and supporters of hepatocarcinogenesis." (PMID 37189787, 2023). "Another cross-sectional study carried out on 340 obese individuals found a negative relationship between trunk fat and BMD, vitamin D, osteocalcin, IGF-1, insulin resistance, and inflammatory markers." (PMID 37771449, 2023). "The third factor is a decrease in adiponectin levels, which can lead to marked insulin resistance and a subsequent increase in insulin growth factor-1 (IGF-1) levels." (PMID 36800961, 2023). "It has been reported that insulin resistance directly promotes carcinogenesis in diabetic individuals, and insulin-like growth factor-1 initiates and progresses tumor growth." (PMID 37810918, 2023). "Insulin resistance, hyperinsulinemia, and insulin-like growth factor-1 (IGF-1) are critical factors in the carcinogenic mechanism." (PMID 37234174, 2023). "Moreover, obesity may cause insulin resistance with hyperinsulinemia, further leading to an increase in insulin-like growth factor-1 which then promotes proliferation and inhibits apoptosis through receptor-mediated pathways, resulting in hepatic carcinogenesis." (PMID 36684957, 2022). "The results suggested that IGF-1, myostatin, and insulin resistance were correlated with sarcopenia in elderly patients undergoing HD." (PMID 35371569, 2022). "Insulin resistance is also involved in the formation and aggressive course of intraocular malignancies by enhancing IGF-1 expression, decreasing adiponectin levels, and limiting apoptosis of tumor cells." (PMID 36003786, 2022). "Consistently with previously reported data, the elevation of circulating insulin level and lower serum level of IGF-1 indicates that orchiectomy induced insulin resistance." (PMID 35547008, 2022). "Elevated insulin levels, which represent insulin resistance, can promote cancer through the insulin-like growth factor-1 (IGF-1) pathway." (PMID 35626156, 2022). "Among them, abnormal glucose metabolism, insulin resistance, and increased IGF-1 levels are attracting increasing attention from researchers." (PMID 36003786, 2022). "A reduction in adiponectin from adipose tissue contributed to insulin resistance and increased insulin-like growth factor 1 (IGF-1) levels, which can elicit increased cell proliferation." (PMID 36505861, 2022). "In a recent work, it was indeed demonstrated that IGF1 is strongly negatively associated both with MAFLD characteristics and with insulin resistance." (PMID 36557260, 2022). "Diabetes mellitus is a metabolic disease characterized by long-term hyperglycemia accompanied by insulin resistance, hyperinsulinemia, and increased insulin-like growth factor (IGF)-1 levels." (PMID 36003786, 2022). "Insulin resistance leads to an increase in insulin-like growth factor (IGF)-1, the most powerful activator of cellular proliferation including cancer cells." (PMID 35600376, 2022).
Insulin resistance (continued). "Acquired resistance to GH results, in consequence, in the decrease of insulin-like growth factor level 1 (IGF-1) and GH compensatory growth, which secondarily increases insulin resistance." (PMID 35054072, 2022). "TNF-α and IL-6, as proinflammatory factors, from obese adipose tissue contribute to insulin resistance by impairing insulin receptor activation, upregulating insulin and insulin-like growth factor-1 (IGF-1) levels." (PMID 35964108, 2022). "IGF-1 is essential for normal insulin sensitivity, and dysregulation of IGF-1 synthesis results in the development of insulin resistance." (PMID 35745205, 2022). "This condition can increase insulin resistance and hyperinsulinemia, which elevates IGF-1 availability." (PMID 35684033, 2022). "To explore the effect of RES on ovarian insulin resistance, we detected the expressions of IGF1 and IGF1R." (PMID 36742000, 2022). "IGFALS is also a plasma protein synthesized by the liver, and it improves glucose tolerance and insulin resistance by prolonging the half-life and increasing the circulating concentration of insulin-like growth factor-1." (PMID 35745003, 2022). "Whilst a reduced IGF-1 level is important in the beneficial effects of fasting in preclinical models, insulin resistance is considered to be an equivalent or more important target than IGF-1 amongst patients with cancer." (PMID 34912072, 2022). "Yet, high-intensity circuit training also produced significant elevations of IGF-1 that were accompanied by improvements in the homeostatic model assessment index of insulin resistance (HOMA1-IR)." (PMID 34936049, 2022). "Patients with acromegaly usually have elevated GH and IGF-1 levels, which can lead to insulin resistance and diabetes." (PMID 35248150, 2022). "The purpose of the study was to understand IGF-1, myostatin, and insulin resistance levels correlated with sarcopenia and the role of IGF-1, myostatin, and insulin resistance in the occurrence of sarcopenia in elderly patients undergoing HD." (PMID 35371569, 2022). "Curiously, insulin resistance has been related to serum levels of the growth factor IGF1 and its receptor IGF1R – components of the growth hormone (GH) and energy metabolisms." (PMID 36506063, 2022). "IGF-1 and insulin have a synergistic effect, possibly indicating the level of insulin resistance in the human body." (PMID 36120463, 2022). "Due to these biological actions, in the liver the deficiency of GH and IGF1 favors the development of MAFLD, respectively, by increasing the accumulation of triglycerides in hepatocytes and by causing the development of insulin resistance." (PMID 36557260, 2022). "Pathophysiologically, insulin resistance is present, leading to increased androgen synthesis by IGF-1 in the ovary." (PMID 36499573, 2022). "Hyperinsulinemia due to insulin resistance can both directly stimulate neoplastic growth of the colonic mucosa and indirectly lead to colorectal tumors by increasing insulin-like growth factor-1 level." (PMID 35668493, 2022). "Based on this recent study, IGF-1, myostatin, and insulin resistance were significantly correlated with sarcopenia in elderly patients undergoing hemodialysis." (PMID 35371569, 2022). "In this study, we investigated the correlation between IGF-1 levels, myostatin levels, and insulin resistance and sarcopenia in elderly patients undergoing HD." (PMID 35371569, 2022). "IGF-1 also promotes glucose uptake in muscle cells; in humans, IGF-1 levels are reduced in condition of insulin resistance, and low IGF-1 levels are associated with the presence of diabetes’ complications." (PMID 36140405, 2022). "Insulin resistance is a pathological condition in which cells fail to sense and respond normally to insulin, with decreased insulin/insulin-like growth factor 1 (IGF-1) signaling (IIS)." (PMID 36465171, 2022).
Insulin resistance (continued). "In acromegalic patients, these mechanisms, amplified by the action of GH and IGF-1, seem to have a more significant impact on the onset of tumors, compared to insulin resistance." (PMID 33713207, 2021). "As we mentioned in the preface, several studies have evaluated the correlation between IGF-1 and insulin resistance in adults." (PMID 34485526, 2021). "This interaction between IGF-1 and insulin signaling pathways has an important role in hyperglycemia/insulin resistance–induced cardiac hypertrophy and fibrosis in the diabetic heart." (PMID 34205870, 2021). "These are likely responsible for the overstimulation of cytokines leading to insulin resistance and IGF-1 resistance." (PMID 35118400, 2021). "The authors also suggested that this was due to transient insulin resistance during pregnancy and increased secretion of IGF-1." (PMID 34769010, 2021). "To dissect how endothelial insulin and IGF-1 resistance contributes to whole-body insulin sensitivity in the pathological context of diet-induced insulin resistance, we fed mIGFREO and WT littermates a high-fat diet (HFD) for 10 days." (PMID 34420367, 2021). "Several studies have reported an increased risk of insulin resistance and T2DM in subjects with low IGF-1 serum concentrations." (PMID 33544228, 2021). "Insulin resistance, hyperinsulinemia and subsequent hyperglycemia, overproduction of insulin like growth factor 1 (IGF-1) and increased secretion of inflammatory cytokines are considered as the most important factors related." (PMID 34768861, 2021). "Insulin resistance significantly increases insulin secretion, which in turn influences bone metabolism via insulin-like growth factor 1 (IGF-1)." (PMID 34769010, 2021). "The deficits in cerebral glucose utilization in human AD include insulin deficiency, insulin-like growth factor 1 (IGF-1) deficiency, and insulin resistance." (PMID 34360973, 2021). "Nonetheless, it still remains controversial with the relationship between IGF-1 and insulin resistance." (PMID 34485526, 2021). "Ang II impairs Akt and mTORC1 signalling by inhibiting the IGF1 signalling axis while simultaneously promoting atrogene transcription, alongside inducing ROS production as well as insulin resistance via inhibition of IRS1 via protein kinase C (PKC) activation." (PMID 33225593, 2021). "The inhibition of insulin/IGF-1 signaling evokes insulin resistance, a condition known to be increased with aging." (PMID 34476533, 2021). "Accordingly, the main purpose of this study is to investigate the relationship between IGF-1 and insulin resistance in obese prepubertal boys." (PMID 34485526, 2021). "It is well established that insulin resistance exerts a critical role in the pathogenesis of HCC by increasing insulin growth factor-1 (IGF-1), which has important proliferative, antiapoptotic and angiogenesis effects." (PMID 35154012, 2021). "Studies have demonstrated the impact of tumor size and levels of IGF-1 and GH on the degree of insulin resistance." (PMID 33859902, 2021). "IGF-1 is a polypeptide protein substance structurally similar to insulin, and its insufficient expression or abnormal phosphorylation would lead to insulin resistance." (PMID 34899946, 2021). "Despite the different genetic causes of SMA and SBMA, both exhibit liver damage and functional deficit in the IGF1 pathway, suggesting a potential link between fatty liver, insulin resistance, IGF1, and neuromuscular damage." (PMID 34072857, 2021). "Conversely, increased IGF-1 levels are paralleled with improvements in insulin sensitivity in premenopausal obese women with insulin resistance consuming a calorie-restricted diet." (PMID 33816541, 2021). "Similar to what occurs in healthy cells during diabetes and insulin resistance, EC cells develop abnormalities in the insulin and insulin-like growth factor-1 (IGF-1) signalling pathways, both of which are involved in cancer cell growth." (PMID 33946913, 2021).
Insulin resistance (continued). "In glucose-resistant overweight to obese patients, ER reduced insulin resistance and insulin-like growth factor 1 (IGF1) levels, but this effect seems only transient and limited to the weight-loss phase—except if accompanied by a reduction in protein intake." (PMID 33809187, 2021). "IGF1 bears 50% homology to insulin and have the same hypoglycaemic effect, with many studies linking fluctuation in IGF1 levels with metabolic disorder and insulin resistance." (PMID 34940355, 2021). "In this scenario, chronic low-grade inflammation and insulin resistance create a suitable microenvironment for the development of cancer by stimulating the insulin growth factor-1 (IGF-1) axis through hyperinsulinemia." (PMID 34259747, 2021). "Obesity is an established risk factor for intracranial tumors, and promotes tumor development through chronic insulin resistance, hyperinsulinemia and enhanced IGF-1 activity." (PMID 34970226, 2021). "These complications which impair IGF-1 signaling to some extent usually include insulin resistance, metabolic acidosis, inflammation, and so on." (PMID 33986663, 2021). "A diet rich in carbohydrates with a high GI is associated with the occurrence of hyperglycaemia, hyperinsulinemia and increased production of insulin-like growth factor 1 (IGF-1) as well as development of insulin resistance." (PMID 34205209, 2021). "For example, IGF-1 mimics some of the insulin actions and promotes insulin sensitivity, while GH is anti-insulinemic and promotes insulin resistance; IGF-1 promotes fat deposition, while GH is lipolytic." (PMID 34899820, 2021). "Combined insulin and IGF-1 resistance restricted to the endothelium leads to a potentially favorable adaptation in contrast to pure insulin resistance, with increased Nox4-derived H2O2 generation mediating enhanced whole-body insulin sensitivity." (PMID 34420367, 2021). "Overall, our results suggest GH and IGF1 resistance in addition to insulin resistance during the first weeks of life in SGA neonates." (PMID 34447729, 2021). "Oxidative stress, insulin resistance, and hyperglycemia promote expression of some cardiomyocyte hypertrophic genes like insulin-like growth factor 1 (IGF-1) receptor, β-myosin heavy chain, or B-type natriuretic peptide." (PMID 34205870, 2021). "Biological mechanism such as the insulin resistance/insulin like growth factor-1 axis, enriched humoral factors such as adipokines, pro-inflammatory cytokines have been addressed 39-41." (PMID 34149912, 2021). "Higher cancer risk in diabetic patients can be related to the following metabolic disorders: hyperglycemia, insulin resistance, hyperinsulinemia, and elevated level of insulin-like growth factor type 1 (IGF-1)." (PMID 34489495, 2021). "Although the mechanism of MetS in the development of CRC is not clear, it is thought to be related to hyperinsulinism and insulin resistance, which increases insulin-like growth factor-1 levels." (PMID 32075578, 2020). "Insulin resistance and alteration in the insulin-like growth factor-1 (IGF-1) contribute to obesity-related colorectal carcinogenesis." (PMID 32454872, 2020). "Nonetheless, its over-production modulates maternal IGF-1, resulting in peripheral insulin resistance." (PMID 33333828, 2020). "Studies have indicated an interplay between IGF-1 and adiponectin to influence the development of obesity, insulin resistance, diabetes, and cancer." (PMID 32456644, 2020). "The insulin resistance induces a relevant bioavailability of insulin-like growth factor-1 (IGF-1), and a consequent downstream activation of the PI3K/Akt pathway, which leads to a deregulated cell proliferation and inhibition of apoptosis." (PMID 32325965, 2020). "Phosphorylation of IRS-1 induces its protein degradation and insulin resistance, thereby inhibiting the insulin-like growth factor 1 (IGF-1) -mediated PI3K activation." (PMID 32932888, 2020).